TNF (tumor necrosis factor)
Diseases named in the same sentence as TNF in open-access papers (continued):
Sharing a sentence is not in itself a finding about the gene and the disease.
Alzheimer disease (continued). "In case of Alzheimer’s disease patients treated with this type of DFPP, a significant reduction in the concentration of RANTES, fibrinogen, sCRP, ECP, TNF-α, and α2-macroglobulin (a marker of neuronal injury and generally increased in Alzheimer’s disease) was evident." (PMID 35745071, 2022). "The binding of these six components to inflammatory mediators (IL-6, TNF-α, IL-1β) and Alzheimer’s disease-related protein targets was studied by molecular docking technology, and it was found that these six components all have low binding energy and good binding fraction." (PMID 36296486, 2022). "To determine if the increase in brain TNFα is specific to areas affected in neurodegenerative disorders such as Alzheimer’s disease (AD), we dissected out the hippocampus, a structure important for learning and memory, and the cortex, from cohort 2 mice (n = 6 mice/dosage group)." (PMID 35897073, 2022). "Stress granules form within many cell types during extended periods of cellular stress, including oxidative stress, heat shock, TNF-α exposure, and aging, and have been postulated to function as scaffolds for aggregation-prone proteins in Alzheimer’s disease and other neurodegenerative disorders." (PMID 34772945, 2021). "In controls, cortical perfusion declined with increasing IFN-γ, IL-2, IL-4, IL-6, IL-10, IL-12p70, IL-13 and tumour necrosis factor-α (TNF-α) but these relationships were lost with progression of Alzheimer’s disease, and with infection (even in Braak stage 0–II brains)." (PMID 33723589, 2021). "TNF-α is an important inflammatory cytokine responsible for mediating and sustaining an inflammatory response in many cell types, including microglia, and clinical evidence has brought to light associations between TNF-α, aging, and Alzheimer’s disease." (PMID 33850164, 2021). "Consistent with our results, previous research has shown that treatment with naproxen at doses of 5–20 μM could reduce the expression of TNF-α in a rat model of Alzheimer’s disease." (PMID 34427537, 2021). "Modelling of acute systemic infection in rodents induces microglial activation and elevated pro-inflammatory cytokine production (IL-1β, IL-6 and TNF-α), and exacerbates cognitive decline, neurodegeneration, and Alzheimer’s disease-like (amyloid-β and tau) pathology in mouse models." (PMID 33723589, 2021). "Microglia-derived sEVs can mediate neuroinflammation by secreting pro-inflammatory mediators such as tumor necrosis factor-α, IL-1β, and miR-155 in traumatic brain injury 44, 45; they are also known to spread the disease by tau propagation in Alzheimer's disease." (PMID 33391532, 2021). "Interestingly, we found that poly I:C- and TNFα-treated human astrocytes exhibit shared gene expression changes with astrocytes from both Alzheimer’s disease and multiple sclerosis patients." (PMID 34172753, 2021). "Among these cytokines, TNF plays a key role, especially in Alzheimer’s disease (AD)." (PMID 33579029, 2021). "In addition, ligand–receptor pairs were involved in some canonical signaling pathways (such as the TNF signaling pathway, NF-kappa B signaling pathway and PI3K-Akt signaling pathway) and certain aging-associated diseases (such as Alzheimer’s disease)." (PMID 34737765, 2021). "This activation state can be induced in vitro by stimulation with lipopolysaccharide (LPS), interferon-γ (IFNγ), tumor necrosis factor (TNF)-α or other inflammatory mediators such as aggregated amyloid-β (Aβ), which is one of the key pathogenic hallmarks during Alzheimer’s Disease." (PMID 33375006, 2020). "TNF‐α participates in a wide range of human diseases including Alzheimer's disease and cancer." (PMID 32761844, 2020). "Furthermore, elevated levels of TNF have been described in many neurodegenerative situations such as in Alzheimer's disease (AD), multiple sclerosis (MS), amyotrophic lateral sclerosis (ALS), and PD." (PMID 33293946, 2020).
Alzheimer disease (continued). "In addition, Alzheimer’s disease (AD) model mice, which are deficient in PDE4B, show decreased TNFα expression in response to inflammatory stimuli." (PMID 32438615, 2020). "Interestingly, VIP and SST are implicated in the pathogenesis of neurodegenerative diseases, including Alzheimer's disease and Parkinson's disease (PD) through reducing the production of inflammatory mediators such as TNF-α and IL-1β." (PMID 32410857, 2020). "Exercise was able to reduced TNFα and IL-1β levels in transgenic model of Alzheimer Disease." (PMID 32320382, 2020). "Recent scientific studies showed that the administration of Epimedium flavonoids improved learning and memory ability through the suppression of microglia and astrocyte activation, resulting in a decrease in the production of IL-1β and TNF-α in the hippocampus of an Alzheimer’s disease mouse model." (PMID 32664577, 2020). "More specifically, TNF-α is upregulated in patients with Alzheimer’s disease." (PMID 32920547, 2020). "Therefore, dysregulation of TNF-α production promotes the development of many human diseases, such as Alzheimer’s disease, cancer, and inflammatory lung disease." (PMID 32373302, 2019). "In addition, the properties of TNFα imply that TNFα blockers are useful as a therapy for many different diseases like Alzheimer’s disease or as an adjuvant for cancer treatment." (PMID 30818829, 2019). "Besides the TLR/TNFα/apoptosis/necroptosis pathway as a driver of neurodegeneration in Alzheimer’s disease, we identified a distinct TLR7/IL-6/apoptosis axis in viral neural pathogenesis mediated by TLR7 upon EV71 infection in vivo." (PMID 31730654, 2019). "Research has demonstrated that TNF-α inhibitors may have possible prophylactic or ameliorating roles in cardiovascular and Alzheimer’s disease in animal models." (PMID 29686666, 2018). "Furthermore, it was previously reported that the cerebrospinal fluid levels of TNF-α strikingly increased in vascular dementia and Alzheimer's disease patients." (PMID 30662512, 2018). "Levels of interleukin (IL)-6 and tumor necrosis factor (TNF)-α (pg/mL) released by peripheral whole blood cells of adult and elderly healthy subjects, as well as of mild Alzheimer’s disease (mAD) and severe Alzheimer’s disease (AD) patients, after 4 h of culture in basal conditions." (PMID 29375582, 2017). "Here we show that in a Drosophila Alzheimer’s disease model, enterobacteria infection exacerbated progression of Alzheimer’s disease by promoting immune hemocyte recruitment to the brain, thereby provoking TNF-JNK mediated neurodegeneration." (PMID 28634323, 2017). "Moreover, in Alzheimer’s disease, during amyloid beta-peptide aggregation, microglia cells are activated and thus the production of TNF-α is stimulated, promoting neuronal death." (PMID 27294919, 2016). "An association between chronic inflammation and chronic neurodegeneration has been found in numerous investigations of Alzheimer disease, where activated microglial cells are closely related to amyloid beta deposits and show increased levels of tumor necrosis factor alpha." (PMID 26597538, 2015). "In addition, oleamide significantly suppressed TNF-α production in microglia derived from the Aβ-deposited brain of Alzheimer’s disease model mice." (PMID 25760987, 2015). "A crucial role of TNFα has also been reported in Alzheimer’s disease (AD)." (PMID 26345473, 2015). "Alzheimer’s disease is also closely associated with low-grade chronic inflammation as highlighted by a number of increased systemic inflammation markers including C-reactive protein (CRP), fibrinogen, interleukin-6 (IL-6), and tumor necrosis factor α (TNF-α)." (PMID 25225492, 2014). "Activation of the TLR pathway increases the expression of various pro-inflammatory cytokines, like IL-6, IL-1 and TNF-α.While earlier evidence has been obtained in the field of Alzheimer’s disease (AD) and Multiple Sclerosis (MS), recent studies have implicated TLRs also in the pathogenesis of PD." (PMID 25099483, 2014).
Alzheimer disease (continued). "Not surprisingly, TNF-α is involved in several neurodegenerative disorders associated with neuroinflammation and neuronal cell death such as Alzheimer's disease (AD), Parkinson's disease, and HIV-associated dementia." (PMID 24065916, 2013). "Moreover, increasing basic science, genetic, and clinical evidence now supports the concept that excess TNF-α plays a central role in Alzheimer's disease (AD)." (PMID 21194439, 2010). "Further study of the effects of etanercept and TNF at the level of the choroid plexus may yield valuable insights into the pathogenesis of Alzheimer's disease." (PMID 19284700, 2009). "The authors hypothesize that excess TNF-alpha in Alzheimer's disease interferes with the synaptic regulatory functions of TNF-alpha." (PMID 18184433, 2008). "Rapid cognitive improvement following perispinal etanercept may be related to amelioration of the effects of excess TNF-alpha on synaptic mechanisms in Alzheimer's disease and provides a promising area for additional investigation and therapeutic intervention." (PMID 18184433, 2008). "It is hoped that future studies may clarify if maintenance perispinal etanercept treatment will help to maintain or restore TNF-alpha homeostasis in the brain and/or cerebrospinal fluid in patients with Alzheimer's disease." (PMID 18184433, 2008). "The authors suggest that a similar duality occurs with respect to TNF-alpha in Alzheimer's disease." (PMID 18184433, 2008). "Excess TNF-alpha in the cerebrospinal fluid has been documented not only in Alzheimer's disease, but also in frontotemporal dementia and vascular dementia, so that all of these may be included in the category of TNF-alpha-mediated dementias." (PMID 18644112, 2008). "The observed expression of cytokines TNF-α and IL-1β by activated glial cells, is consistent with expression of these cytokines in brains of experimental animal models of Alzheimer's and in the brain of Alzheimer's disease patients." (PMID 16174294, 2005). "Thus, TNF-α as a potential biomarker for Alzheimer's disease progression." (PMID 41960503, 2026). "Evidence suggests that RA patients treated with anti-TNF agents may have a reduced risk of developing Alzheimer’s disease compared to controls, whereas such an association has not been observed with other DMARDs." (PMID 40805961, 2025). "Studies have demonstrated that in the pathological microenvironment of Alzheimer’s disease (AD), amyloid-beta (Aβ) deposition and abnormally phosphorylated Tau protein can induce the activation of microglia and astrocytes, which in turn secrete tumor necrosis factor-α (TNF-α)." (PMID 41450541, 2025). "For example, elevated levels of pro-inflammatory cytokines such as interleukin-6 (IL-6) and tumor necrosis factor-α (TNF-α), commonly linked to gut dysbiosis in Alzheimer’s disease, have also been reported in ALS patients and may accelerate disease progression." (PMID 41184709, 2025). "Research indicates that TNF-α is one of the main neuroinflammatory mediators, responsible for microglial activation, which leads to the release of additional pro-inflammatory cytokines, such as IL-1β, exacerbating neurodegenerative processes in Alzheimer’s disease." (PMID 40137151, 2025). "Therefore the role of TNF‐α in Alzheimer's disease models requires further exploration." (PMID 37528567, 2024). "Importantly, recent clinical data suggest that at least for Alzheimer’s disease, anti-TNFα antibodies might be protective." (PMID 37365324, 2023). "In addition, they may release inflammatory mediators, including IL-1 and TNF-α, inducing neuroinflammation in the brain of a person suffering from Alzheimer’s disease." (PMID 37047492, 2023). "In Alzheimer’s disease, β-amyloid plaques are surrounded by reactive glial cells (microglia and astrocytes) showing elevated expression of proinflammatory factors such as IL-1β, IL-6, TNF-α, and nitric oxide, while anti-inflammatory cytokines (TGF-β1 and IL-10) are at reduced levels." (PMID 36298702, 2022).
Alzheimer disease (continued). "Uro B intervention was found to reduce levels of IL-1β, IL-6 and TNF-α in brains of a mouse model of D-gal-induced Alzheimer disease (AD)." (PMID 35814202, 2022). "Previous studies illustrated that Th17 cells were found in the vicinity of neuritis plaques in AD brains, along with increased pro-inflammatory cytokines (IL-1β, IL-6, CXCL1, and TNF-α) in peripheral blood, which may contribute to the development of Alzheimer’s disease." (PMID 35669784, 2022). "Thus, aloe polymannose shows potential as a therapy in cases of cognitive and immune dysfunction, such as Alzheimer’s disease (AD), which is characterized by chronic inflammation and neurodegeneration, marked by increased production of inflammatory cytokines, such as TNF-α." (PMID 34239993, 2021). "Interestingly, both VIP and SST were reported to exert protective effects in neurodegenerative diseases, including Alzheimer's disease and PD through inhibiting the microglial activation and expression of the cytotoxic mediators, such as TNF-α, IL-1β, and prostaglandin E2." (PMID 32410857, 2020). "Interestingly, our data indicated that the increased TNF-α in the NTS was associated with baroreflex dysregulation and aberrant hemodynamics, which is similar to observations in Alzheimer’s disease and Parkinson’s diseases, suggesting a link between TNF-α and neuronal dysfunction in the NTS." (PMID 31729994, 2019). "Tumor necrosis factor-α (TNF-α) has been documented as a cytokine that plays a critical role in neuroinflammation linked to neurodegeneration in a number of diseases, including MS, Parkinson’s, and Alzheimer’s disease; many of its effects are mediated by NF-κB activation." (PMID 24479486, 2014). "Alzheimer's dementia is typified by activation of microglia and astrocytes in response to Aβ deposition, leading to a release of a variety of factors including the cytokines TNFα and IL-1β, free radicals such as nitric oxide, superoxide and cyclo-oxygenase pathway derived prostanoids." (PMID 25414636, 2014). "However, persistent activation of microglial cells is believed to contribute to neurodegenerative disease such as Alzheimer’s disease, Parkinson’s disease and amyotrophic lateral sclerosis; through increasing the release of pro-inflammatory mediators or cytokines, including NO, TNF-α and ROS." (PMID 22489138, 2012). "The positive clinical effects the authors have observed using perispinal etanercept for chronic treatment of Alzheimer's disease on an open-label basis, now for a period exceeding three years, suggest that maintenance anti-TNF-alpha treatment may have prolonged beneficial effects." (PMID 18184433, 2008). "The TNFα pathway was also significantly upregulated (GAGE analysis demonstrates 91 genes with an adjusted P value of 8.5 × 10− 2), as was the Alzheimer’s disease term (305 genes with an adjusted P value of 1.4 × 10− 1)." (PMID 40542358, 2025). "Elevated levels of pro-inflammatory cytokines (IL-6, TNF-α, IL-1β, and IFN-γ) are observed in elderly individuals, leading to increased risks of atherosclerosis, type 2 diabetes, Alzheimer’s disease (AD), and osteoporosis." (PMID 40843723, 2025). "In Alzheimer’s disease (AD), GMF expression is reduced and improves neuroinflammatory responses by inhibiting pro-inflammatory cytokines (TNF-α, Il-1β, and IL-1)." (PMID 39114368, 2024). "By reducing cytokine production as well as decreasing microglial activation, siRNAs that target TNF-α or NLRP3 inflammasome components, for example, have shown significant effectiveness in preclinical models of Parkinson’s and Alzheimer’s diseases." (PMID 39852123, 2024). "Several SASP factors, including IL-6, IL-1β, TNF-α, MMP-1, MMP-3, and MMP-10, have also been found to be elevated in the cerebrospinal fluid and serum of patients with Alzheimer’s disease." (PMID 37569663, 2023).
Alzheimer disease (continued). "β-Asarone protects cognitive function by inhibiting ACh esterase and suppressing tumor necrosis factor-α (TNF-α) and interleukin-1β (IL-1β) secretion among Alzheimer’s disease-induced rats." (PMID 36340563, 2022). "Chronic neuroinflammation is one of the main drivers of Alzheimer’s disease, and JQ1 treatment has reduced the expression levels of the pro-inflammatory modulators IL-6, IL-1β, and TNF-α, suggesting promise in the treatment of neurological disorders." (PMID 35154163, 2022). "The cytokine tumor necrosis factor (TNF) mediated this heterodendritic metaplasticity in wild-type rodents and in a mouse model of Alzheimer’s disease." (PMID 35110639, 2022). "TNF-α/TNFR1-induced necroptosis occurs in several neurodegenerative diseases of the CNS, such as multiple sclerosis (MS), Parkinson’s disease and Alzheimer’s disease." (PMID 35806192, 2022). "This illustrates that during pathological conditions including Alzheimer's disease (AD), TNF-α is harmful for memory function and synaptic plasticity, and TNF-α inhibition can be used to effectively manage the disease." (PMID 35937071, 2022). "Tumor necrosis factor-α (TNF-α) is a pleiotropic, proinflammatory cytokine related to different neurodegenerative diseases, including Alzheimer’s disease (AD)." (PMID 36037389, 2022). "Seven terms from the WP database were enriched: histone modifications, TNF-alpha-NF-kB signalling, EGFR1 signalling, MAPK signalling, Alzheimer’s disease, oxidative damage, and apoptosis." (PMID 33964983, 2021). "For instance, peripheral administration of the soluble TNF inhibitor XPro1595 has been shown to rescue impaired LTP in 5xFAD mice, a mouse model of Alzheimer’s disease, together with a decreased beta-amyloid load." (PMID 33588894, 2021). "In mice, peptides from milk reduced the expression of inflammatory factors such as TNF-α, monocyte chemoattractant protein-1 (MCP-1/CCL2) or inducible nitric oxide synthase (iNOS) in the hippocampus in a model of Alzheimer’s disease." (PMID 33801489, 2021). "Oral administration of a bioactive milk tripeptide inhibits the expression of inflammatory factors such as TNF-α, CCL2 or iNOS in the hippocampus of the Alzheimer’s disease mice model." (PMID 33801489, 2021). "This prompted a recently initiated lenalidomide Alzheimer’s disease clinical trial (MCLENA-1), as lenalidomide is a more potent second-generation analog against TNF-α within the IMiD drug class." (PMID 34361041, 2021). "In a triple-transgenic mouse model of Alzheimer disease, neuroprotection D1 (NPD1) (50 nM) downregulates Aβ42-induced expression of COX-2, TNF-α, and B-94, a TNF-α-inducible pro-inflammatory element." (PMID 34638979, 2021). "Another study showed that calycosin treatment decreased the levels of TNF‐α, interleukin (IL)‐6, IL‐1β, and MDA in acute pancreatitis (AP) mice and Alzheimer's Disease mouse." (PMID 32910538, 2020). "A similar improvement of PPARγ expression has been previously reported for OC-rich EVOO in the brain of Alzheimer’s disease mice model, and for the EVOO simple phenol hydroxytyrosol, a precursor of OA, in TNF-α-stimulated SGBS cells." (PMID 31766503, 2019). "Elevated levels of TNFα are present in ASD patients, as well as in numerous neurological disorders including multiple sclerosis, Alzheimer's Disease, Parkinson's Disease, ischemia, and traumatic brain injury." (PMID 27812316, 2016). "According to this, blocking of IL-17A in a wild-type mouse model of lung Ad resulted in a decreased number of Foxp3+ Tregs and an increase of IFN-γ and TNF-α producing CD4+ T cells leading to a significant reduction of tumor growth." (PMID 22855687, 2012). "TNFα is upregulated in several neurodegenerative disorders (cerebral malaria, AIDS dementia, Alzheimer's disease) and has been primarily considered to promote the pathologies." (PMID 21143912, 2010).